ZNF445 (zinc finger protein 445)
Description:
Transcription regulator required to maintain maternal and paternal gene imprinting, a process by which gene expression is restricted in a parent of origin-specific manner by epigenetic modification of genomic DNA and chromatin, including DNA methylation. Acts by controlling DNA methylation during the earliest multicellular stages of development at multiple imprinting control regions (ICRs). Acts together with ZFP57, but seems to be the major factor in human early embryonic imprinting maintenance. In contrast, in mice, ZFP57 plays the predominant role in imprinting maintenance.
Synonyms: ZFP445; ZKSCAN15; ZNF168; ZSCAN47
Tractability: PROTAC: UniProt records ubiquitination sites on it; ubiquitination databases record sites on it.
Gene: Protein-coding gene on chromosome 3 (44,431,705 to 44,477,693, reverse strand). Ensembl gene ENSG00000185219.
Subcellular location: Nucleus
Subcellular location (Human Protein Atlas): Nucleoplasm; Cytosol; Mitochondria
Pathways (Reactome):
Gene expression (Transcription): Generic Transcription Pathway
Gene Ontology:
Molecular function: double-stranded methylated DNA binding; protein binding; chromatin binding
Biological process: epigenetic programing of female pronucleus; negative regulation of gene expression via chromosomal CpG island methylation; regulation of transcription by RNA polymerase II; regulation of DNA-templated transcription
Cellular component: nucleus
Genetic constraint (gnomAD): Loss-of-function variants: 19 observed, 92.85 expected, observed/expected ratio (o/e) 0.2, 90% interval 0.14 to 0.3. The upper end of that interval is the gene's LOEUF score, 0.3, which puts it in group 1 of 6, group 1 being the genes least tolerant of losing a copy. Missense variants: 1,057 observed, 1,308.7 expected, observed/expected ratio (o/e) 0.81, 90% interval 0.77 to 0.85. Synonymous variants: 449 observed, 468.69 expected, observed/expected ratio (o/e) 0.96, 90% interval 0.89 to 1.04.
Homologues: Orthologues: chimpanzee ZNF445 (99% identical), macaque ZNF445 (98% identical), dog ZNF445 (79% identical), rabbit ZNF445 (78% identical), pig ZNF445 (77% identical), guinea pig ZNF445 (62% identical), mouse Zfp445 (59% identical), rat Zfp445 (59% identical), zebrafish prdm2a (8% identical), Caenorhabditis elegans ztf-16 (8% identical), Caenorhabditis elegans sdz-12 (7% identical), Caenorhabditis elegans ehn-3 (6% identical), and 1 more. Paralogues in human: ZNF786 (21% identical), ZNF211 (20% identical), ZNF462 (18% identical), ZNF521 (15% identical), ZNF423 (15% identical), ZNF597 (12% identical), ZBTB39 (8% identical).
Diseases named in the same sentence as ZNF445 in open-access papers:
ZNF445 is named in the same sentence as 10 diseases in open-access papers, as found by Europe PMC text mining. Sharing a sentence is not in itself a finding about the gene and the disease. The quoted sentences say what the papers report.
Temple syndrome (3 papers, 2021 to 2024). "Here we report the first ZNF445 pathogenic variant identified in a patient with Temple syndrome (TS14) and MLID." (PMID 34039421, 2021). "Re-analysis of the previously obtained whole exome sequencing data identified a homozygous ZNF445 variant (NM_181489.6:c.2803C>T:p.(Gln935*)) producing a truncated protein missing two of 14 zinc finger domains in a patient with Temple syndrome and MLID." (PMID 34039421, 2021). "Indeed, the discovery of a pathogenic variant of ZNF445 responsible for Temple syndrome and multi-locus imprinting disorders confirms its role in imprinting mechanisms." (PMID 38909248, 2024). "Since ZNF445 binds to the MEG3/DLK1:IG-DMR and other iDMRs affected in this patient, the development of Temple syndrome and MLID would primarily be explained by the ZNF445 variant." (PMID 34039421, 2021).
depression (1 paper, 2025). "Another positively selected depression-associated SNP is located in the gene ZNF445, which is involved in post-fertilization methylation maintenance and imprinting disorders." (PMID 40075226, 2025). "Unlike the SNP in FADS1, the SNP in ZNF445 has an OR for allele T on rs2372688 of 0.98 (p = 0.000006758), suggesting a protective effect against depression." (PMID 40075226, 2025).
hydatidiform mole (1 paper, 2022). A gestational trophoblastic disorder characterized by marked enlargement of the chorionic villi, hyperplasia of the villous trophoblastic cells and hydropic changes. "Pathological variants of zinc finger protein genes such as ZFP57 and ZNF445 and of genes related to the subcortical maternal complex such as NLRP2, NLRP5, NLRP7, and KHDC3L have been identified in cases of multilocus imprinting disturbances (MLIDs) and recurrent hydatidiform moles (RHMs)." (PMID 35581658, 2022).
neonatal diabetes mellitus (1 paper, 2021). Neonatal diabetes mellitus presents as hyperglycemia, failure to thrive and, in some cases, dehydration and ketoacidosis which may be severe with coma, in a child within the first months of life. "Furthermore, previous studies in search of a ZNF445 variant(s) have been performed for MLID-positive patients diagnosed with transient neonatal diabetes mellitus (n = 3), BWS (n = 28), and PHP-Ib (n = 10)." (PMID 34039421, 2021).
ZNF445 also shares sentences with these, for which no sentence is quoted: breast carcinoma (1 paper); metabolic syndrome (1); multiple myeloma (1); ovarian carcinoma (1); uterine cancer (1); Williams syndrome (1).